GRIA3 (glutamate ionotropic receptor AMPA type subunit 3)
Description:
Ionotropic glutamate receptor that functions as a ligand-gated cation channel, gated by L-glutamate and glutamatergic agonists such as alpha-amino-3-hydroxy-5-methyl-4-isoxazolepropionic acid (AMPA), quisqualic acid, and kainic acid (By similarity). L-glutamate acts as an excitatory neurotransmitter at many synapses in the central nervous system and plays an important role in fast excitatory synaptic transmission by inducing long-term potentiation (By similarity). Binding of the excitatory neurotransmitter L-glutamate induces a conformation change, leading to the opening of the cation channel, and thereby converts the chemical signal to an electrical impulse upon entry of calcium. The receptor then desensitizes rapidly and enters a transient inactive state, characterized by the presence of bound agonist. In the presence of CACNG8, shows resensitization which is characterized by a delayed accumulation of current flux upon continued application of glutamate.
Synonyms: GluR-3; GluA3; GLUR3; GLURC; MRX94; GluR-C; GluR-K3; iGluR3; MRXSW
Tractability: Small molecule: an approved drug acts on it; a high-quality ligand is known; it belongs to a druggable protein family. Antibody: UniProt places it where antibodies can reach, with high confidence; its Gene Ontology location is reachable by antibodies, with high confidence; UniProt predicts a signal peptide or a membrane-spanning region. PROTAC: its protein half-life has been measured; a small molecule that binds it is known.
Target class: Ligand-gated ion channel; Ionotropic glutamate receptor; AMPA receptor; Ion channel
Safety:
Unwanted effects reported when the protein is acted on. In parentheses: how it was acted on, where the effect was seen, and who reports it.
treatment-emergent suicidal ideation (source: ClinPGx)
Gene: Protein-coding gene on chromosome X (123,184,023 to 123,490,915, forward strand). Ensembl gene ENSG00000125675.
Subcellular location: Cell membrane; Postsynaptic cell membrane; Postsynaptic density membrane
Pathways (Reactome):
Neuronal System: Activation of AMPA receptors; Synaptic adhesion-like molecules; Trafficking of AMPA receptors; Trafficking of GluR2-containing AMPA receptors; Unblocking of NMDA receptors, glutamate binding and activation
Gene Ontology:
Molecular function: AMPA glutamate receptor activity; glutamate-gated receptor activity; ligand-gated monoatomic ion channel activity involved in regulation of presynaptic membrane potential; protein binding; amyloid-beta binding; glutamate-gated calcium ion channel activity; transmitter-gated monoatomic ion channel activity involved in regulation of postsynaptic membrane potential; ligand-gated monoatomic ion channel activity; monoatomic ion channel activity; signaling receptor activity
Biological process: protein heterotetramerization; protein homotetramerization; glutamate receptor signaling pathway; long-term synaptic potentiation; modulation of chemical synaptic transmission; synaptic transmission, glutamatergic; calcium-mediated signaling; ionotropic glutamate receptor signaling pathway; monoatomic ion transmembrane transport; monoatomic ion transport; regulation of postsynaptic membrane potential; regulation of presynaptic membrane potential
Cellular component: plasma membrane; AMPA glutamate receptor complex; dendritic spine; endocytic vesicle membrane; postsynaptic density membrane; postsynaptic membrane; membrane
Gene-disease validity (ClinGen):
ClinGen rates the evidence that GRIA3 causes each of these diseases.
X-linked complex neurodevelopmental disorder (X-linked): Definitive. A complex neurodevelopmental disorder that is transmitted via X-linked inheritance, and is characterized by intellectual disability, autism and epilepsy.
Homologues: Orthologues: chimpanzee GRIA3 (99% identical), macaque GRIA3 (99% identical), dog GRIA3 (99% identical), pig GRIA3 (99% identical), rabbit GRIA3 (99% identical), guinea pig GRIA3 (99% identical), rat Gria3 (99% identical), mouse Gria3 (99% identical), zebrafish gria3b (87% identical), zebrafish gria3a (86% identical), tropical clawed frog gria3 (82% identical), Drosophila melanogaster GluRIB (46% identical), and 38 more. Paralogues in human: GRIA4 (73% identical), GRIA2 (69% identical), GRIA1 (67% identical), GRIK2 (38% identical), GRIK1 (38% identical), GRIK3 (36% identical), GRIK4 (35% identical), GRIK5 (35% identical), GRID1 (28% identical), GRID2 (27% identical), GRIN1 (25% identical), GRIN2A (22% identical), and 5 more.
Diseases named in the same sentence as GRIA3 in open-access papers:
GRIA3 is named in the same sentence as 66 diseases in open-access papers, as found by Europe PMC text mining. Sharing a sentence is not in itself a finding about the gene and the disease. The quoted sentences say what the papers report.
schizophrenia (12 papers, 2009 to 2026). A major psychotic disorder characterized by abnormalities in the perception or expression of reality. "PTVs of GRIA3 have been identified as high-risk variants for schizophrenia from the exome analysis, as has XPO7." (PMID 39774335, 2025). "We meta-analyzed large-scale brain transcriptomic data from mice harboring individual loss-of-function mutations in seven schizophrenia risk genes (Akap11, Dagla, Gria3, Grin2a, Sp4, Srrm2, Zmym2)." (PMID 41022686, 2025). "These genes encompass high-odds risk genes of schizophrenia identified by SCHEMA, including Gria3, Grin2A, Herc1, and Trio." (PMID 39774335, 2025). "The involvement of Gria3 in Xpo7-mediated pathological pathways is significant in its impact on schizophrenia-related pathology." (PMID 39774335, 2025). "Nine genes are robustly associated with schizophrenia through deleterious mutations in these genes: SETD1A, CUL1, XPO7, TRIOCANCA1G, SP4, GRIA3, GRIN2A, and HERC1." (PMID 38911007, 2022). "Previously, common polymorphic variants from the promoter regions of GRIA1, GRIA3, GRIN1, or GRIN2A were associated with susceptibility to addiction, migraine, or schizophrenia." (PMID 34945722, 2021). "In our dataset, we detected AMPA and NMDA receptor subunits associated with schizophrenia (i.e., GRIA1 and GRIN2A) and with a spectrum of DD/ID, ASD and seizures, often in co-morbidity (GRIA3, GRIN1, GRIN2A, and GRIN2B)." (PMID 28713243, 2017). "Also, a large-scale exome sequencing study identified single genes whose rare mutations substantially increase the risk for schizophrenia, of which six genes (SETD1A, CUL1, XPO7, GRIA3, GRIN2A, and RB1CC1) showed odds ratios larger than ten." (PMID 36878965, 2023). "By contrast, the non-DD/ID mutants (Akap11+/−, Dagla+/−, Gria3−/y, Sp4+/−) showed upregulation of these schizophrenia, NDD, and ASD gene sets in the thalamus." (PMID 41022686, 2025). "Meanwhile, mutant mice originally created not as a schizophrenia model but to elucidate gene function in the central nervous system, such as knockout mice for GRIN2A or GRIA3 encoding a glutamate receptor subunit, have not been subjected to omics analysis." (PMID 36878965, 2023).
Cognitive impairment (9 papers, 2015 to 2025). Abnormal cognition is characterized by deficits in thinking, reasoning, or remembering. "More specifically, GRIA3 AMPA-receptor mutations have been associated with intellectual impairment and SCZ." (PMID 38343691, 2024). "Finally, mutations in GRIA3 have been associated with cognitive impairment." (PMID 27453991, 2016). "Blockage of the AMPA and NMDA receptors in mature neural systems has been shown to decrease the density of dendritic spines which is then postulated to result in SCZ like symptoms and cognitive impairments Furthermore, the published GWAS studies suggest that GRIA3 and GRIN2A to be dysregulated." (PMID 38343691, 2024).
epilepsy (9 papers, 2014 to 2025). A brain disorder characterized by episodes of abnormally increased neuronal discharge resulting in transient episodes of sensory or motor neurological dysfunction, or psychic dysfunction. "Pathogenic GRIA3 variants cause X-linked neurodevelopmental disorders of varying severity, including developmental delay, behavioral abnormalities, and epilepsy." (PMID 41462794, 2025). "Numerous epilepsy cases associated with GRIA3 mutations have been reported, with a higher occurrence among males." (PMID 39774335, 2025). "Here we identified a pathogenic missense variant in GRIA3 gene in a female patient with severe epilepsy and global developmental delay." (PMID 34161333, 2021). "Two de novo variants have been reported in females, one with bipolar symptom and ID who carries a balanced translocation involving GRIA3, and another with epilepsy for whom a de novo p.A248V variant was identified." (PMID 34161333, 2021). "In this study, a de novo variant in GRIA3 was identified by clinical whole genome sequencing in a 1-year-old female with severe epilepsy and global developmental delay." (PMID 34161333, 2021). "Significance: This case expands the clinical and molecular spectrum of GRIA3-related disorders, demonstrating that females with de novo variants may experience severe epilepsy." (PMID 41462794, 2025). "GRIA3 gene mutations seem to result in a broad spectrum of neurodevelopmental disorders, with heterogeneous epileptic manifestations, generally with early onset, potentially classified as the combination of a generalized type of epilepsy of genetic origin and focal seizures." (PMID 41462794, 2025). "These include the AMPAR subunit genes GRIA1, GRIA3, and GRIA4, causing an NDD spectrum including ID, loss of speech, epilepsy, gait abnormalities, and abnormal sleep patterns." (PMID 31300657, 2019). "As example, loss-of-function mutations in the gene, Glutamate Receptor, Ionotropic, AMPA 3 (GRIA3), lead to an XLMR, with frequent comorbid seizure disorder and autistic features." (PMID 25477785, 2014). "However, GRIA3-related epilepsy seems potentially classified as the combination of generalized and focal seizures with genetic origin." (PMID 41462794, 2025). "Although there are several publications describing the safety and efficacy of PER for individuals with epilepsy, there are no similar data available in individuals with GRIA3 GoF variants." (PMID 34161333, 2021).
migraine (8 papers, 2008 to 2021). "GRIA1 and GRIA3 (subunits GluR1 and GluR3) gene polymorphisms are considered potential predisposing/causative factors for migraine." (PMID 27191890, 2016). "Another association analysis on Italian population have reported two genes that code for subunits of the ionotropic AMPA receptors GRIA1 and GRIA3 have been implicated in migraine." (PMID 26800698, 2015). "The previous studies have reported the glutamate receptor ionotropic GRIA1 and GRIA3 genes variants associated with migraine." (PMID 26800698, 2015). "Amongst various gene polymorphisms in the glutamatergic system, only the Glutamate Receptor Ionotropic AMPA 3 (GRIA3) was previously associated with migraine." (PMID 28132339, 2015). "Two SNPs in GRIA1 (5q33.2, rs548294 MO allelic P=0.008, rs2195450 MA allelic P=0.0005) and 1 SNP in GRIA3 (rs3761555 MA Females allelic P=0.003) showed a positive association with migraine." (PMID 23675283, 2013). "We found two variants in GRIA1 gene (rs548294 and rs2195450) and one variant in GRIA3 gene (rs3761555), all located in the regulative region of the genes, to be associated with the migraine phenotype in an Italian population." (PMID 20579352, 2010). "Regarding GRIA3 gene, we obtained statistically significant evidence for an association to migraine phenotype for the -1952T/C variant (rs3761555) located in the regulative region of the gene (allele C frequencies: controls-migraineurs = 22% vs. 34%)." (PMID 20579352, 2010). "Future genetic and functional studies are necessary to further elucidate the role of GRIA3 in migraine susceptibility." (PMID 20579352, 2010). "Therefore, the -1952T>C polymorphism may affect the GRIA3 promoter binding affinity with nuclear proteins and in turn the GRIA3 expression, which consequently modulates the individual's susceptibility to migraine." (PMID 20579352, 2010). "Further remarkable in our cohort is that GRIA1 and GRIA3 variants are associated to migraine in female but not in male subjects." (PMID 20579352, 2010). "Furthermore, our analysis of the combined effects of the two SNPs in GRIA1 (rs548294) and GRIA3 (rs3761555) genes not supported a synergy of the two SNPs in the genetic susceptibility to migraine." (PMID 20579352, 2010). "In this study we investigated the association of GRIA1, GRIA2, GRIA3 and GRIA4 genes that encode for the four subunits (GluR1-GluR4) of the alpha-amino-3-hydroxy-5-methyl-4-isoxazole-propionic acid (AMPA) ionotropic receptor and their variants to migraine with and without aura (MA and MO)." (PMID 20579352, 2010).
Intellectual disability (7 papers, 2014 to 2025). "The most likely causal variant identified was a novel missense variant in the X-linked GRIA3 gene, which has been implicated in intellectual disability." (PMID 29016847, 2017). "Furthermore, GRIA3 has been implicated in numerous disorders in the brain including bipolar disorder, mental retardation, and encephalopathy with epileptic seizures (Rasmussen encephalitis)." (PMID 27453991, 2016). "Among them, LAMP2, GRIA3, PHF6, and HPRT1 genes are associated with Danon disease, Intellectual deficiency, X-linked syndrome, Wu type, BFL syndrome, Lesch Nyhan syndrome and other syndromes." (PMID 38031145, 2023). "An early work found that a female with bipolar disorder and intellectual disability carried a balanced translocation affecting GRIA3." (PMID 34161333, 2021).
Alzheimer disease (6 papers, 2013 to 2024). A progressive, neurodegenerative disease characterized by loss of function and death of nerve cells in several areas of the brain leading to loss of cognitive function such as memory and language. "Although GRIA3 has not been associated with AD, glutamate receptors have been studied (including members in the same family of genes as GRIA3) for their effect on Alzheimer’s disease based on the hypothesis that malfunction of glutamate receptors leads to AD-specific cell loss." (PMID 27453991, 2016).
cognitive decline (6 papers, 2011 to 2025). "Among these proteins, only GRIA3 was detected in our datasets and had lower-abundance in faster cognitive decline in both Banner and BLSA, consistent with Bereczki and colleagues’ finding." (PMID 30962425, 2019). "A recent study investigating X chromosome gene expression found that several genes (including GRIA3, GPRASP2, and GRIPAP1) were associated with slower cognitive decline in women but not men." (PMID 39231932, 2024).
depression (6 papers, 2009 to 2025). "GRIA3 has been implicated in multiple intellectual developmental disorders and depression." (PMID 41208600, 2025).
developmental delay (6 papers, 2017 to 2025). "In the GRIA3 gene encoding another glutamate receptor (GluA3), a variant at the homologous amino acid as lurcher was identified in two patients with developmental delay and a disturbed sleep–wake cycle (GRIA3 p.Ala653Thr; SYTANLAAFL)." (PMID 37944084, 2024). "Here, we report a 7-year-old female with developmental delay, spastic gait, and non-convulsive status epilepticus (NCSE) carrying a novel de novo GRIA3 variant." (PMID 41462794, 2025). "Case Summary: Here, we present the case of a seven-year-old female patient presenting with developmental delay, spastic gait, and non-convulsive status epilepticus (NCSE), who was found to carry a novel de novo GRIA3 missense variant (c.1969A > G; p.Thr657Ala)." (PMID 41462794, 2025).
bipolar disorder (4 papers, 2009 to 2023). A disorder of the brain that causes unusual shifts in mood, energy, activity levels and the ability to carry out day-to-day tasks. "Since GRIA3 encodes a glutamate receptor subunit that forms a ligand-gated ion channel responsive to glutamate, the predominant excitatory neurotransmitter in the brain, this gene may be of relevance to bipolar disorder and irritable mania in particular." (PMID 23326512, 2013). "GRIA3 plays an important role in excitatory synaptic transmission and is involved in bipolar disorder and nonspecific X-linked mental retardation." (PMID 37069190, 2023).
breast carcinoma (4 papers, 2014 to 2023). "Other risk factors, such as HPX and GRIA3, have been reported in many cancers, including glioma, breast cancer and pancreatic cancer." (PMID 31907037, 2020). "Expression of GRIA2 and GRIA3 mRNA was induced by hypoxia in Hep3B cells but not in two breast cancer cell lines." (PMID 25326682, 2014).
Epileptic encephalopathy (4 papers, 2021 to 2024). A condition in which epileptiform abnormalities are believed to contribute to the progressive disturbance in cerebral function. "Here, we report a female patient with developmental and epileptic encephalopathy who carries the novel de novo GRIA3 variant NM_007325.5: c.1982T > C: p.Met661Thr." (PMID 36726007, 2023). "Functional analyses of a GRIA3 missense variant leading to epileptic encephalopathy and global DD showed that mutant GluA3 receptors resulted in slower desensitization and deactivation kinetics in human embryonic kidney 293T (HEK293T) cells and slower ESPCs in neurons." (PMID 35457207, 2022). "Notably, functional studies revealed that the gain of function variant in GRIA3 might cause epileptic encephalopathy and global developmental delay in a female subject by enhancing synaptic transmission." (PMID 39596051, 2024). "Therefore our study provides functional evidence that a gain of function (GoF) variant in GRIA3 may cause epileptic encephalopathy and global developmental delay in a female subject by enhancing synaptic transmission." (PMID 34161333, 2021). "The AMPAR subunit gene most commonly associated with ID is GRIA3, which is also linked to ASD, global DD, seizures, and/or epileptic encephalopathy." (PMID 35457207, 2022).
glioma (4 papers, 2014 to 2023). A benign or malignant brain and spinal cord tumor that arises from glial cells (astrocytes, oligodendrocytes, ependymal cells). "Expression of GRIA3 and other glutamate receptors has been associated with the development and progression of gliomas and neuroblastomas." (PMID 31498117, 2019). "GRIA1 and GRIA3 were shown to promote tumor progression in glioma and pancreatic cancer." (PMID 25326682, 2014).
pancreatic cancer (4 papers, 2014 to 2022). "GRIA3, as glutamate receptor, is involved in the process of tumor progression in pancreatic cancer." (PMID 35488327, 2022). "Additionally, GRIA3 is an important mediator of tumor progression in pancreatic cancer in vitro and in vivo." (PMID 31498117, 2019).
alcoholism (3 papers, 2012 to 2014). "The top candidate genes that we identified include genes which have previously been associated with alcoholism, such as Gabrg2, Gabrb3 and Gria3, but also genes that have not been associated with alcoholism before." (PMID 22629472, 2012).
lung carcinoma (3 papers, 2019 to 2024). "MiR-330-3p is also related to metastasis and invasion of lung cancer, and glutamate receptor 3 (GRIA3) and human manganese superoxide dismutase 2 (hSOD2) are its two target genes." (PMID 32948197, 2020). "We also observed that TGF-β1 and GRIA3 were co-expressed in lung cancer patient samples in the MEM database." (PMID 31498117, 2019). "We searched the R2 database to determine any association between GRIA3 and TGF-β1 in lung cancer patient populations." (PMID 31498117, 2019). "Interestingly, we found a dataset showed that GRIA3 was negatively correlated with TGF-β1 in a set of lung cancer patients (R = -0.455, P = 0.0053)." (PMID 31498117, 2019). "These genes include GRIA3, TAF7L, ARL14, PCDHGA9, MDGA1, ZFPM2, OSR2, TMC8/TMC6, HCN2, and CDK5R2, which are likely to be relevant in human lung cancer and are also epigenetically deregulated upon exposure to ECS in our animal study." (PMID 39273313, 2024).